ICAM1 (intercellular adhesion molecule 1)
Diseases named in the same sentence as ICAM1 in open-access papers (continued):
Sharing a sentence is not in itself a finding about the gene and the disease.
lung carcinoma (91 papers, 2011 to 2025). "Palbociclib upregulates the transcription of ICAM-1 by inhibiting the phosphorylation of RB in LKB1-deficient lung cancer animal model, which is essential for NK cell surveillance." (PMID 41463246, 2025). "Icam1 overexpression enhanced the homing and activation of tumor-specific T cells in Lkb1-deficient lung cancer." (PMID 36871040, 2023). "Together, these data confirmed that LKB1 deficiency is associated with suppression of ICAM1 in lung cancer." (PMID 36871040, 2023). "Regarding the underlying mechanisms, one investigation demonstrated increased ICAM-1 expression as a cause of the antimetastatic effect of CBD on lung cancer cells, with the effect being reversed by an ICAM-1 neutralising antibody." (PMID 35277658, 2022). "Additional studies have shown that ICAM-1 in the systemic circulation of lung cancer patients can bind to leukocyte-function associated antigen-1 of cytotoxic lymphocytes in the blood, enabling cancer cells to evade immune recognition mechanisms." (PMID 32195055, 2020). "THC and CBD have been reported to stimulate the expression of the intercellular adhesion molecule 1 (ICAM-1) on lung cancer cells to enhance the susceptibility of cancer cells towards lysis by lymphokine-activated killer cells." (PMID 33126623, 2020). "Here we show that celecoxib, but not other structurally related COX-2 inhibitors, induces an upregulation of ICAM-1 expression on lung cancer cells, thereby causing increased cancer cell lysis by LAK cells." (PMID 26513172, 2015). "The data presented here suggest LFA-1 as a crucial counter-receptor of ICAM-1 in conferring the celecoxib-induced enhanced susceptibility of lung cancer cells to LAK cell-mediated killing." (PMID 26513172, 2015). "High expression of ICAM-1 in human lung cancer specimens was correlated with a greater risk of advanced cancers (stages III and IV)." (PMID 24901215, 2014). "Both THC and CBD, as well as methanandamide (an AEA analogue), have been shown to promote the expression of ICAM-1 on lung cancer cell lines, resulting in an increased susceptibility of tumor cells to lysis mediated by lymphokine-activated natural killer cells." (PMID 40804975, 2025). "Accordingly, cannabinoids, a group of substances with diverse anticarcinogenic properties, have been shown to enhance the susceptibility of lung cancer cells to cytolytic death mediated by lymphokine-activated killer (LAK) cells via increase of ICAM-1 on cancer cell surface." (PMID 26513172, 2015). "We found that elevated HELLS and decreased ICAM1 mRNA levels are predictive of poor prognoses in lung cancer patients, which could significantly improve our understanding of the causes and potential molecular events of lung cancer." (PMID 32195055, 2020). "Palbociclib enhances the transcription of ICAM1 by inhibiting the phosphorylation of Rb, ultimately leading to the activation of CD8+ T cells in LKB1-deficient lung cancer animal model." (PMID 41463246, 2025). "(2014) reported that CBD upregulates ICAM-1 expression on lung cancer cells, enhancing their adhesion to lymphokine-activated killer (LAK) cells, leading to a cytotoxic effect." (PMID 40599866, 2025). "The adhesion of lipopolysaccharide-activated neutrophils to cancer cells was mediated by neutrophil Mac-1/ICAM-1 in lung cancer." (PMID 40564191, 2025). "(2012) found that CBD inhibits lung cancer cell invasion by inducing tissue inhibitor of metalloproteinases-1 (TIMP-1) through intercellular adhesion molecule-1 (ICAM-1) activation." (PMID 40599866, 2025). "To evaluate the anti-lung cancer effect, we estimated three anti-lung cancer biomarkers: Intercellular Adhesion Molecule-1(ICAM-1), MYC proto-oncogene, bHLH transcription factor(c-MYC), and Matrix metalloproteinase-9 (MMP9) genes." (PMID 39338293, 2024). "Expression of intercellular adhesion molecule 1 (ICAM-1) has been correlated with a better prognosis in colorectal and lung cancer." (PMID 38228372, 2024).
lung carcinoma (continued). "In vitro studies showed that leptin enhanced production of soluble intercellular adhesion molecule-1 (ICAM-1) in lung cancer cells through triggering a signaling cascade involving JAK1/2, STAT3, FAK, ERK, and GSK3αβ." (PMID 38571500, 2024). "ICAM-1 can promote the formation of CTC (circulating cancer cell) clusters in lung cancer, by promoting cell aggregation." (PMID 39199664, 2024). "CBDs have been shown to increase the lysis of lung cancer cells by lymphokine-activated killer cells via upregulation of Intercellular Adhesion Molecule 1 (ICAM-1)." (PMID 38558822, 2024). "NNK administration stimulated inducible lung cancer biomarkers, including (i) ICAM-1 level, c-MYC, and MMP9 genes, (ii) inflammation, (iii) angiogenesis, and (iv) proliferation." (PMID 39338293, 2024). "Chia treatment caused a recovery effect as there was a significant decrease in ICAM-1 level in the chia ether group (397.97 ± 7.55 pg/mL) and the chia alcohol group (491.67 ± 6.54 pg/mL) in the comparison to the lung cancer control." (PMID 39338293, 2024). "It’s prospective to attenuate ICAM-1–expressing lung cancer progression as well as other ICAM-1‒expressing solid tumor growth by blocking ICAM-1–FGG ligation." (PMID 39168965, 2024). "NSCLC patients with high neoplastic ICAM-1 expression and serum soluble ICAM-1 levels show more aggressive lung cancer progression, suggesting a potential role of ICAM-1 in promoting NSCLC." (PMID 39168965, 2024). "CBD has been shown to exhibit anti-invasive and antimetastatic properties against lung cancer cells in a dual mechanism involving intercellular adhesion molecule-1 (ICAM-1)." (PMID 38891847, 2024). "Haustein and colleagues reported that CBD promotes the expression of ICAM-1 on lung cancer cells as a target for their anti-invasive and antimetastatic actions." (PMID 38891847, 2024). "To demonstrate this finding further, we examined ICAM1 expression across a panel of LKB1 mutant versus LKB1 wild-type lung cancer cell lines." (PMID 36871040, 2023). "Based on the observation that RT induces PD-L1, CXCL10, and ICAM-1 at the same time, RT combined with anti-PD-1 immunotherapy is suggested in clinical practice for patients with lung cancer." (PMID 36688994, 2023). "CBD was found to increase TIMP-1 and ICAM-1 expression in a dose-dependent manner in lung cancer cell lines and inhibited the spread and invasion of human lung cancer xenografts in mice, partially due to the increase in ICAM-1 and TIMP-1." (PMID 37397476, 2023). "We brought forward that ICAM1 on cancer cells orchestrates the antitumor immunity, which is prerequisite for the homing and activation of effector T cells for LKB1 deficient lung cancer." (PMID 36871040, 2023). "Ropivacaine treatment was shown to have beneficial antimetastatic effects on NCI-H838 lung cancer cells, potentially by suppressing tumor necrosis factor-α-induced src-activation and intercellular adhesion molecule-1 phosphorylation." (PMID 38034873, 2023). "Considering the key role of ICAM1 in response to ICIs, we sought to find a clinically accessible approach to restore the expression of ICAM1 in LKB1 deficient lung cancer." (PMID 36871040, 2023). "The vaccine targeting ICAM-1 is also at the early stage of clinical investigation against ICAM-1 overexpressing bladder cancers or lung cancer (NCT02043665)." (PMID 37006265, 2023). "In this study, the application of luteolin effectively reduces the expressions of PM2.5-induced pro-metastatic factors, such as pro-MMP-2 and ICAM-1, in human lung cancer H460 cells." (PMID 36185331, 2022). "In contact with a svPLA2, a reduction in the expression and invasion of ICAM-1 in lung cancer cells was observed." (PMID 35745643, 2022). "We observed that luteolin reduced cell migration and the expression of pro-metastatic factors pro-matrix metalloproteinase (MMP)-2 and intercellular adhesion molecule (ICAM)-1 in PM2.5-exposed H460 lung cancer cells." (PMID 36185331, 2022).
lung carcinoma (continued). "Using flow cytometry we detected a 2.7-fold upregulation of ICAM-1 in MB-PDT-treated lung cancer cells compared to untreated cells 24 h post-treatment and 6.4-fold upregulation in MB-PDT-treated cells 48 h post-treatment." (PMID 36077656, 2022). "The upregulation of ICAM-1 was found in several types of cancer, such as breast and lung cancer—the major cancer killers." (PMID 35741337, 2022). "The oncogenic role of ICAM1 in promoting tumor stemness has been identified in lung cancer, hepatocellular carcinoma, and esophageal squamous cell carcinoma." (PMID 36264639, 2022). "Further research by the same group investigated the role of ICAM-1 in the effect of cannabinoids on lung cancer cell lines A549, H460, and H358." (PMID 36437760, 2022). "Low-dose IFN-γ enhanced the stemness and metastasis of non–small cell lung cancer via the intercellular adhesion molecule-1 (ICAM1)-PI3K-Akt-Notch1 axis." (PMID 35747815, 2022). "In contrast, DAC-treated lung cancer cells with normal ICAM-1 expression established immune synapses with a prominent synaptic cleft between cancer and γδ T cells." (PMID 33846331, 2021). "Another study found a causal relationship in lung cancer cells between THC-, CBD- and Met-AEA-induced invasion inhibition and the induction of the expression of intercellular adhesion molecule-1 (ICAM-1), which acts as an upstream regulator of TIMP-1." (PMID 34830856, 2021). "Evidence suggests that ICAM-1 is involved in cancer progression and promotes distant metastasis of tumors, such as those present in liver cancer, colorectal cancer, and lung cancer." (PMID 33754027, 2021). "Another synthetic sPLA2 inhibitor is the molecule S3319 that, in lung cancer cells, decreases ICAM-1 expression levels and, subsequently, reduces cancer cell invasion." (PMID 34208346, 2021). "On the other hand, overexpression of ICAM1 (OV-ICAM1) in lung cancer cell lines with a Tet-On system markedly enhanced γδ T cell-mediated cytotoxicity on human lung cancer cells, mimicking the effect of DAC pretreatment." (PMID 33846331, 2021). "Apoptosis of lung cancer cells is suppressed by Tet treatment through the VEGF/HIF-1α/ICAM-1 pathway." (PMID 33763489, 2021). "In a later study, the same group found that intercellular adhesion molecule-1 (ICAM1) was upregulated by cannabidiol-elicited TRPV1-activation-mediated p42/44 activation in lung cancer cell lines A549, H358, and H460, subsequently inhibiting cell invasion." (PMID 34131404, 2021). "When we knocked out ICAM1 in H1299 lung cancer cells, there was a substantial decrease in DAC-induced F-actin accumulation at immune synapses, which was associated with a significant reduction in synaptic cleft width." (PMID 33846331, 2021). "Western blotting confirmed that DAC can significantly upregulate ICAM-1 proteins in many lung cancer cell lines as well as a patient-derived lung cancer cell line from a malignant pleural effusion, PDC#062." (PMID 33846331, 2021). "Overexpression of ICAM1 had been reported in several malignancies, including renal cell carcinoma, pancreatic cancer, and lung cancer." (PMID 33072116, 2020). "Previous studies have shown that inhibition of ICAM1 decreases metastasis in melanoma and lung cancer." (PMID 33072116, 2020). "CBD also upregulated the expression of surface protein intercellular adhesion molecule (ICAM-1) in lung cancer cells, which correlated with decreased metastasis of these cells." (PMID 32708138, 2020). "Other studies have shown that cannabinoid-induced ICAM-1 can increase LAK cell-mediated tumor cell killing ability in lung cancer, a novel antitumor mechanism of cannabinoids." (PMID 32195055, 2020). "ICAM1, a member of an immunoglobulin‐like superfamily of adhesion molecules, is involved in various processes in lung cancer development and signal transduction across leukocyte‐epithelial cell interactions." (PMID 33377642, 2020).
lung carcinoma (continued). "RT-qPCR results showed that HELLS expression in lung cancer tissues was upregulated when compared with normal tissue, while ICAM1 expression in lung cancer tissues was downregulated when compared with normal tissue." (PMID 32195055, 2020). "In combination with a series of previous studies, we found that decreased ICAM1 mRNA levels predict poor prognoses in patients with lung cancer." (PMID 32195055, 2020). "An improved prognosis was associated with increased Helicase, Lymphoid-Specific (HELLS) and decreased Intercellular adhesion molecule 1 (ICAM1) mRNA expression in lung cancer patients." (PMID 32195055, 2020). "It has been shown that thalidomide can suppress ICAM1 expression and inhibit invasion mediated by ICAM1 in lung cancer." (PMID 31467533, 2019). "THC, CBD, and R(+)‐methanandamide (an endocannabinoid analogue) have been shown to promote the expression of ICAM‐1 on lung cancer cell lines A549, H460, and metastatic cells derived from a lung cancer patient." (PMID 29473338, 2018). "The alternative transcript uc010xle/AK301412 (ICAM1) was differentially expressed in lung cancer; the mRNA level of one was increased in 36.7% (11 of 30, p < 0.05) and decreased in 40% (12 of 30, p < 0.05)." (PMID 28105922, 2016). "Altogether, our data demonstrate celecoxib-induced upregulation of ICAM-1 on lung cancer cells to be responsible for intercellular ICAM-1/LFA-1 crosslink that confers increased cancer cell lysis by LAK cells." (PMID 26513172, 2015). "This process requires the binding of CD11b/CD18 on M2a macrophages to ICAM-1 on A549 lung carcinoma cells." (PMID 26231039, 2015). "Time-course experiments revealed a significant upregulation of ICAM-1 protein expression in lung cancer cells after a 48-h incubation with 30 μM celecoxib." (PMID 26513172, 2015). "Receptor activator of nuclear factor-κB ligand-triggered tumor migration was demonstrated in a lung cancer model via upregulation of intercellular adhesion molecule-1 (ICAM-1)." (PMID 24432249, 2014). "Ursolic acid (3β-hydroxy-urs-12-en-28-oic acid) was identified to inhibit the cell-surface ICAM-1 expression induced by pro-inflammatory cytokines in human lung carcinoma A549 cells." (PMID 24970122, 2011). "Compared with normal lung tissues, the expression of MMP3, MMP9, and PPARG was increased in lung cancer tissues, and the expression of ALOX5 and ICAM1 was decreased in lung cancer tissues, which was basically consistent with the analysis results in the GEPIA database." (PMID 39440769, 2025). "On the other hand, oral administration of chia extracts for five months significantly reduced lung cancer biomarkers, including the relative weight of the lung, ICAM-1, c-MYC, and MMP9 gene expression, and lung histology was improved considerably compared to the lung cancer control one." (PMID 39338293, 2024). "ICAM-1, the lung cancer biomarker, was significantly increased by NNK injection." (PMID 39338293, 2024). "The use of statins may prevent the increase in total cholesterol and ICAM-1 concentration after irradiation for lung cancer; however, further studies designed for this specific purpose are necessary to confirm the effectiveness of statins in this area." (PMID 38928407, 2024). "Subsequently, we sought to address whether ICAM1 correlates with augmented CD8+ T cells in lung cancer patients’ samples." (PMID 36871040, 2023). "We found that high levels of the 5 genes, PD-L1, ICAM-1, CXCL10, IRF1, and TAP1, were correlated with better survival probabilities in lung cancer patients treated with immunotherapies (N = 21, p = 0.17 for PD-L1, p = 0.28 for ICAM-1, p = 0.052 for CXCL10, p = 0.023 for IRF1, and p = 0.22 for TAP1)." (PMID 36688994, 2023). "The levels of Tenascin C and VEGFA were higher in the MPE of EGFR-mutated lung cancer patients but not Fibronectin, ICAM-1, nor PAI-1." (PMID 37649596, 2023).
lung carcinoma (continued). "In our study, comparing MYADM with other known lung cancer biomarkers by bioinformatic methods, we found MYADM was associated with ICAM1 and RAC1, suggesting that MYADM may be a prognostic factor for NSCLC." (PMID 36061144, 2022). "Furthermore, CBD treatments rendered lung cancer cells more likely to attach to and be destroyed by lymphokine-activated killer (LAK) cells, and it was discovered that the overexpression of ICAM-1 was the cause of LAK cells’ enhanced activity." (PMID 36297340, 2022). "It is known that the increase of ICAM-1 expression may indicate the poor prognosis in lung cancer patients, which played an important role in the development and metastasis of lung cancer." (PMID 36061144, 2022). "ICAM-1 assists with tumor extravasation in lung cancer via the binding of neutrophils." (PMID 35252243, 2022). "As TIMP-1 upregulation is prevented by ICAM-1 neutralizing antibodies or silencing microRNA, the authors concluded that the cellular adhesion and signaling molecule ICAM-1 are implicated in the beneficial effects of cannabinoid compounds on lung cancer." (PMID 36437760, 2022). "In A549, H460 NSCLC cells, and metastatic cells derived from a lung cancer patient, CBD (3 μM) elevated the susceptibility of these lung cancer cells to lymphokine-activated killer (LAK) cell-mediated tumor-cell killing in an ICAM-1-dependent manner." (PMID 35741337, 2022). "In addition, studies also suggest that CBD can increase the activity of a protein known as the intercellular adhesion molecule (ICAM-1) in lung cancer cells, which is known to decrease the spread of disease." (PMID 36297340, 2022). "ICAM1 also plays an important role in the development of different carcinomas, and its reduction suppresses the metastasis of cancers such as liver, breast, colorectal 36 and lung cancer." (PMID 33811439, 2021). "Therefore, JWH133 increased TIMP-1 production in lung cancer cells and induced ICAM-1 expression, thereby modifying the tumor cell microenvironment and inhibiting angiogenesis." (PMID 34393784, 2021). "Additionally, CBD treatment increased the susceptibility of lung cancer cells to adhere to and subsequently be lysed by lymphokine-activated killer (LAK) cells, and that the upregulation of ICAM-1 was responsible for the increased action of LAK cells." (PMID 32708138, 2020). "ICAM-1 blockade inhibited lung cancer cell invasion in vitro and tumor metastasis in vivo." (PMID 33005178, 2020). "From these three datasets, we identified that ICAM-1 is dysregulated in lung cancer." (PMID 32195055, 2020). "Finally, we analyzed the expression of HELLS and ICAM1 in lung cancer patients to determine their expression patterns, potential functions, and different prognostic values." (PMID 32195055, 2020). "In addition to M-CSF, among the inflammatory factors analyzed in our study, MCP-1 and IL-6 were increased, whereas eotaxin-2 and ICAM-1 were decreased in lung cancer cells overexpressing Oct4." (PMID 32487125, 2020). "Concerning the mechanisms leading to enhancement of tumor-immune interactions, a recent study found an increase of tumor cell killing via lymphokine-activated killer cells crosslinked by LFA-1 to CBD-, Δ9-THC- and R(+)-methanandamide-induced ICAM-1 on the surface of lung cancer cells." (PMID 31143113, 2019). "has demonstrated that an important part of cannabinoids’ anticancer action may be constituted by the modulation of the expression of the intercellular adhesion molecule 1 (ICAM‐1) on lung cancer cells." (PMID 29473338, 2018). "As an immunoglobulin supergene family member, ICAM1 is shown to be critically involved in adhesion of cancer cells to ECM, in particular, overexpression of ICAM1 correlates with increased tumor malignancy and poor outcome in lung cancer, clear cell renal cell carcinoma, and mouse GBM model." (PMID 29676997, 2018).